TNF (tumor necrosis factor)
Diseases named in the same sentence as TNF in open-access papers (continued):
Sharing a sentence is not in itself a finding about the gene and the disease.
tumor (continued). "In contrast, M1 macrophages increase antigen presentation and enhance tumor cell clearance by secreting pro-inflammatory cytokines, including IL-6, IL-12, and TNF-α." (PMID 35625939, 2022). "Tumor-associated macrophages are abundant in the TME and impede anti-cancer immune responses by generating inflammatory cytokines, such as IL-12, IL-1b, TNF-α, and IL-6." (PMID 36298592, 2022). "TAMs exhibit either an immunosuppressive M2-like phenotype, increasing production of anti-inflammatory factors IL-10 and TGF-β, or an anti-tumor M1-like phenotype, releasing pro-inflammatory cytokines IL-12, IL-1, IL-6, and TNF-α." (PMID 35236203, 2022). "On the one hand, pro-tumorigenic cytokines secreted by neutrophil granulocytes and thrombocytes, including vascular endothelial growth factor, tumor necrosis factor-α, and interleukin-10, have been suggested to contribute to tumor progression." (PMID 35098389, 2022). "Cytotoxic CD8+ T cells kill tumor cells by secreting TNF-α and IFN-γ, while CD4+ T cells produce multiple cytokines to boost anti-tumor immune responses." (PMID 36313283, 2022). "HuR is an RNA-binding protein involved in activating tumor necrosis factor (TNF), which is critical in tumor progression." (PMID 35600860, 2022). "Tumor and host immune cells release pro-cachectic cytokines such as tumor necrosis factor (TNFα), interleukin 1 (IL-1), IL-6, and interferon gamma (IFNγ)." (PMID 35326491, 2022). "In contrast, CD38, whose expression on myeloid cells predicts favourable prognosis hence its anti-tumoural activity in HCC25 and proinflammatory cytokine TNF, were both reduced in S2 and S3 tumours." (PMID 35301339, 2022). "Our data show that soluble Siglec-5 increased the frequency of IL-2, IFN-γ and TNF-α by MEL624 tumor antigen specific CD4 T cells." (PMID 35290663, 2022). "RelA has been reported to upregulate PD-L1 in tumour cells in response to TNF-α and LPS stimulation or by cooperation with RB phosphorylation." (PMID 35177112, 2022). "The activation and polarization of CD4+ T cells into Th1 phenotype is accompanied by a heightened ability to produce and secrete effector cytokines such as IFN-γ and TNF-α that have direct anti-tumor activities." (PMID 36605208, 2022). "M1 macrophages produce pro-inflammatory molecules that trigger inflammation and execute anti-tumor effects, such as TNF-α, IL-12, IL-23, and iNOS." (PMID 34976223, 2022). "TNFα can potentially act as an angiogenic stimulus, which leads to distinct cell communication in the tumor microenvironment, inducing VCAM-1 expression." (PMID 36290384, 2022). "Destruction of tumor cells by OVs results in the release of tumor-specific antigens (TSA), PAMPs, danger-associated molecular patterns (DAMPs), and cytokines (TNFα, IFNγ, and IL-12)." (PMID 36678780, 2022). "Interaction with other molecules, such as tumor necrosis factor-α, in the tumor microenvironment reveals a complex interplay between IAPs and cancer." (PMID 35406442, 2022). "In fact, it has also been found that endogenous levels of TNFα have some pro-tumorigenic effects by promoting infiltration and functions of immunoregulatory cells, including MDSCs and Treg, and by enhancing tumor cell survival and metastatic potential." (PMID 35269922, 2022). "Mechanistically, MDSCs co-treated with VPA and anti-PD-L1 demonstrated impaired suppressive function and enhanced production of TNFα by T cells for anti-tumor effect." (PMID 35140716, 2022). "PD-1+ regulatory B cells (Bregs) can suppress anti-tumor immunity through suppression of cytotoxic T cell function, a process regulated via TNFα signaling and PD-1 expression." (PMID 35355980, 2022). "In various tumor stem cells, IL-6 is highly expressed by the NF-κB signaling pathway which is triggered by growth factors such as TNF-α and IL-1β." (PMID 36359888, 2022). "Levels of certain cytokines in the tumor microenvironment were also affected: tumor necrosis factor-alpha (TNF-α), IFN-γ, IL-2, and IL-5 were elevated, while IL-6 was decreased." (PMID 36428632, 2022).
tumor (continued). "The activation of NF-κB signaling, induced by TNF-α, has also been shown to be a key element in resistance of apoptosis-based tumor mechanisms." (PMID 35011526, 2022). "Following detection of tumor cells by macrophages, various pathways can kill tumor cells, including contact-dependent phagocytosis and cytotoxicity (i.e., activation of cytokine like TNF-α)." (PMID 35093033, 2022). "This phenomenon, that in C26 tumor bearing mouse models manifests even before the cachexia phenotype is observed, is mainly dependent on TNF-α, which directly impairs insulin signaling and IRS-1 activation." (PMID 35441960, 2022). "The level of TNFα was changed only in the distal part of the colon, it was lower in tumors compared to the control and tumor-adjacent tissues." (PMID 36555251, 2022). "Significant increase in IL4 (control/tumor tissue) (p=0.025) and TNF-α (control/tumor tissue) (p=0.012) levels was revealed." (PMID 35237320, 2022). "As an important pathway in bone homeostasis, the RANK/RANK-L/OPG pathway can be abnormally activated by cytokines secreted from tumor cells such as PTHrP, IL-6, and TNF that can promote osteolytic changes." (PMID 36230816, 2022). "The transcription factor NF-κB can regulate the expression of tumor-promoting genes (IL-6 and TNF-α)." (PMID 35237507, 2022). "Inhibition of SIRT-1 upregulates B7-H3 and TNF-α in the tumor microenvironment, thereby inducing tumor immune escape." (PMID 35906622, 2022). "Three weeks after TP administration, we found that TNF-α alone has little effect on the tumor weight and volume." (PMID 36110523, 2022). "TNFα produces and maintains a network of other mediators that promote tumor growth and peritoneal spread by stimulating the release of IL-6 and other chemokines such as CCL2 and CXCL12, macrophage migration-inhibitory factor (MIF), and VEGF." (PMID 36142615, 2022). "In the early stages of tumorigenesis, TAMs, and in particular M1 macrophages, suppress sprouting angiogenesis and induce vessel maturation by secreting anti-angiogenic cytokines (e.g., IL-12 and TNF-α) and activate an anti-tumor immune response." (PMID 35759090, 2022). "To gain further insight into how HIF1α induces CRC progression, we examined the effect of HIF1α on many microenvironmental genes, including TGF-β, TNF-α, VEGF, EGF, PDGF, b-FGF, HGF, and IGF, which have been implicated in promoting tumor development." (PMID 35355718, 2022). "They modulate the TNF-α signaling via direct and indirect effects on the tumor microenvironment, and they reduce the secretion of FGF-2, VEGF and IL-6 by both MM cells and BMSCs." (PMID 36362718, 2022). "It showed that WGP in vivo trained CD11b+ myeloid cells in the pancreas produced significantly more TNF-α in response to tumor-conditioned media." (PMID 35140221, 2022). "Endogenous chronic TNF-α signaling promotes tumor growth by maintaining MDSCs survival in the transplanted tumor model." (PMID 35280697, 2022). "Although both combinations showed tumor growth inhibition, cabozantinib/nivolumab had enhanced cytotoxic IFNγ and TNFα+ T cells." (PMID 36419897, 2022). "To confirm the inhibition of Fn by SNH, we tested the effects of SNH on the Fn-induced inflammation in vivo, and the inflammatory cytokines TNF-α and IL-1β in the tumor xenografts and colon tissues from the HCT116-engrafted mice were analyzed by qPCR." (PMID 36551597, 2022). "It was found that high level of TNF can inhibit tumor cell growth via inhibition of vascularization, direct cytotoxicity and promoting anti-tumor immunity." (PMID 36376825, 2022). "Increased TNF-α concentration in tumor-infiltrating lymphocytes and CRC tissue is an independent factor of better survival." (PMID 35954156, 2022). "The soluble factors derived from adipocytes, called adipokines, including adiponectin, leptin, IL-6, and tumor necrosis factor α, are involved in tumor progression." (PMID 35805003, 2022).
tumor (continued). "In melanoma, TNF-α signaling via the TNFR-1 receptor causes activated CD8+ T-cells to die and suppresses T-cell-mediated tumor rejection." (PMID 35547942, 2022). "TNF-α diffuses from the tumor to the pituitary gland; an additional source of TNF-α originates in the pituitary gland as ipilimumab (which is infused into the blood) and targets the CTLA-4 expressed on pituitary cells." (PMID 36355837, 2022). "PRDM1 upregulation impaired the CD8+ T cell activation (CD8+GZMB+ T cells) and T cell-mediated tumor cell killing activity (CD8+TNFα+ T cells) in the co-culture, whereas PRDM1 knockout had contrasting effects." (PMID 36509766, 2022). "Consistent with a role of TNFα in liver regeneration, hepatocyte growth is also inhibited, resulting in a shorter lifespan even though tumor burden was reduced." (PMID 36276076, 2022). "Macrophages induce the generation of ROS within tumor cells through secretion of various stimuli, such as TNFα." (PMID 36615330, 2022). "IL-6, IL-8, TGF-β, NFκ and TNF-α are some of the elements shown to play a role in the tumor-induced inflammatory environment." (PMID 35659296, 2022). "Transferring valerate or butyrate-treated cytotoxic T cells and chimeric antigen receptor T cells into tumor-bearing mice increased the production of CD25, IFN-γ, and TNF-α and enhances the anti-tumor activity." (PMID 36296324, 2022). "Lymphocytes can not only prevent cytotoxic cell death, but also secrete IFN-γ and TNF-α to control tumor growth." (PMID 35241010, 2022). "Although TNFα was first discovered as a rapid inducer of necrosis in tumor cells, it was later shown to have contextual roles in cancer." (PMID 35281021, 2022). "We found that stimulation of normal fibroblasts with TNFα, which is actively expressed by tumor cells, leads to similar changes in the fibroblast transcriptome that are observed during co-cultivation with cancer cells." (PMID 36263012, 2022). "For instance, putrescine has been shown to inhibit M1 macrophage activation through downregulating IL-8 and TNF-α expression in a LPS-stimulated inflammation model, thus implying the contribution of M1 macrophage inhibition to immune evasion of tumor cells." (PMID 36119047, 2022). "P5091 decreased the levels of anti-inflammatory cytokine IL-10 and increased proinflammatory IFN-γ and TNF-α in tumor tissue and TME." (PMID 36428632, 2022). "Thymic cancer: curcumin mediated thymic protection happens, at least in part, via neutralization of tumor-induced oxidative stress, restoration of NF-jB activity, and re-education of the TNF-signaling pathway." (PMID 36712505, 2022). "Low levels of TNFα during chronic inflammation can lead to immune escape and tumor growth by activating immunosuppressive cells such as regulatory T cell, regulatory B cells and myeloid-derived suppressor cells." (PMID 36362245, 2022). "It was also found that IL-10-producing Bregs limit anti-tumor immunity via TNF-α and promote tumor development by attenuation of CD8+INF-ƴ+ T cells responses." (PMID 36618354, 2022). "We found significantly higher concentrations of periostin, VEGF-A, IFN-γ, IL-1 β, IL-17 and TNFα in the tumor samples compared with surgical tissue margins." (PMID 35056404, 2022). "S1P‐treated CD8+ T cells also secreted lower levels of cytotoxic cytokines such as IL‐17, TNF alpha, and IFNγ, which further suggest that S1P is immunosuppressive in the tumor microenvironment." (PMID 35289120, 2022). "NK cells differentiate tumor stem cells or undifferentiated tumors by secreting or membrane-bound IFN-γ and TNF-α and prevent tumor growth by modifying the tumor microenvironment." (PMID 36212483, 2022). "Recent descriptions of the role of TNFα in tumor biology has supported the concurrent immunosuppression with anti-TNF molecules." (PMID 35847803, 2022). "As far their effects, tumour‐infiltrating MAIT cells show reduced IFN‐γ and TNF‐α generation, with augmented IL‐17 production, a cytokine able to increase to tumour angiogenesis." (PMID 35344301, 2022).
tumor (continued). "Before testing the effect of CM, we first examined the outcome for the direct application of TNFα to tumor cells." (PMID 35804814, 2022). "Myeloid cells within the tumor microenvironment produce inflammatory mediators such as IL-6 and TNF-a, promoting tumor growth, inflammation, and angiogenesis." (PMID 36230500, 2022). "Andrographolide reduces the expression of adhesion molecules such as ICAM-1 by blocking TNF-α-induced Akt phosphorylation in tumor cells, thereby suppressing tumor cell metastasis." (PMID 35682652, 2022). "Mechanistic experiments showed that gut microbiota activated Toll-like receptor 4 (TLR4), resulting in modulation of tumor-infiltrating immune cells toward a pro-inflammatory, TNF+ phenotype." (PMID 35474500, 2022). "Melissoidesin G has the ability to inhibit TNF-α, induced NF-κB transcriptional activation and induce tumor cell apoptosis." (PMID 36408214, 2022). "In line with the role played by αCTLA-4, we observed a statistically significant induction of a neoantigen-specific CD4+TNFα+ in tumor-bearing mice." (PMID 35110563, 2022). "These cells in their functional state also produce increased levels of TNFα and iNOS, which contribute to the killing of tumor cells." (PMID 35205790, 2022). "Considering that FLS can be activated by TNF-α and IL-1β and exhibit biological behaviours similar to tumour cells, we used IL-1β and TNF-α to treat human RA-derived FLS MH7A cells to construct RA cell models." (PMID 36405992, 2022). "The platelet-derived growth factor (PDGF) secreted by tumor cells can be recognized by NKp44 triggering NK cell secretion of interferon-gamma and tumor necrosis factor-alpha to hamper tumor growth." (PMID 36359863, 2022). "For simplicity, when considering levels of TNF-α below a prescribed threshold, we take the average concentration of TNF-α just within the tumor." (PMID 36355837, 2022). "Our data suggest that serum IFN-γ and TNF-α levels were high in the Ayu_ND-treated group relative to the downregulation of these molecules in tumor-bearing animals." (PMID 35444547, 2022). "Again, such differences between in vivo and in vitro results were attributed to higher expression of TNF in the tumor’s microenvironment." (PMID 35406442, 2022). "Following this, M1-like macrophages induced tumor death via secreting IL-6, IL-10, IL-12, and TNF-α." (PMID 36518255, 2022). "In our study, the levels of periostin in the tissue margin correlated positively with the margin and tumor levels of TNFα Additionally, we observed correlation between periostin and TNFα in tumor tissue." (PMID 35056404, 2022). "In contrast with the saline group, the level of IL-6, IFN-γ, and TNF-α in the V+E@Gel group were enhanced by 2-, 1.6-, and 4-fold, respectively, demonstrating the strong and robust immune reaction in tumor tissues." (PMID 36145556, 2022). "CD14+ TGFBI+ M0‐like TAMs compose the greatest proportion of total TAMs and are related to tumor angiogenesis, hypoxic necrosis, and tumor necrosis factor signaling and PI3K–AKT signaling pathways." (PMID 35634956, 2022). "It was found that ligation of MY-1 to SIRPβ1 promoted TNFα secretion by macrophages and suppressed tumor growth through activation of a DAP12-Syk- MAPK signaling pathway." (PMID 35865547, 2022). "Then, M2-polarized macrophages significantly increased secretion of various tumor-active molecules including MMPs, VEGF, and TNFα to induce tumor progression." (PMID 35578228, 2022). "TNF-α can induce tumor immunosuppressive microenvironment formation by activating inflammation-related signaling pathways, as well as promoting tumor angiogenesis and tumor spread." (PMID 36225358, 2022). "Inflammatory cytokines TNF-α can trigger the first step of tumor transformation, act as an autocrine growth factor for tumor cells, and play a major role in metastasis." (PMID 36618075, 2022). "The other type of antibody is called “recessive,” because it cannot overcome a tumor burden with the additional TNF." (PMID 35741080, 2022).
tumor (continued). "Only TNF and CgA followed the trend of the NETest, which showed significant differences between tumor grades." (PMID 36294509, 2022). "Their research emphasized the importance of neutralizing low levels of TNF in the tumor microenvironment in order to sensitize the potential of chemotherapy response for medical use." (PMID 35933373, 2022). "Researches showed that the secretion of pro-inflammatory cytokines, such as TNF-α, can trigger the apoptosis of cancer cells in tumor site." (PMID 36733388, 2022). "This subsequently activates NF-κB, which originates from the autocrine-paracrine loop produced by TNF-α in tumor cells." (PMID 35574296, 2022). "Producing key anti-tumour and immune activation cytokines such as TNF-α, IL-8, IL-2, and IL-22, NKp46 activated ILC3s accumulate significantly in stage I/II in NSCLC patients." (PMID 35557940, 2022). "Soluble TNF-α and tmTNF-α all possess dual abilities to promote tumor growth and survival, while tmTNF-α has much broader anti-proliferative capabilities." (PMID 36591235, 2022). "What was reported, however, was impaired function in tumor infiltrating NK cells, with reduced IFNγ, TNFα, and proliferation." (PMID 35757002, 2022). "TNF-a has been reported to alter the tumor microenvironment (TME), enhance tumor aggressiveness, and promote metastasis." (PMID 36117156, 2022). "Macrophage is the main source of TNFα and among the most abundant support cells in a tumor microenvironment." (PMID 36119107, 2022). "TNF-α secretion by IL-7 stimulation was increased by in CD8+ cells from tumor and para-tumor tissue." (PMID 35850640, 2022). "NK cells help in differentiating stem cells and undifferentiated cancer cells by secreting IFN-γ and TNF-α, which limit the tumor growth by remodeling/regulating the tumor microenvironment." (PMID 36500466, 2022). "Poor overall survival was noted in tumours with high cytokine concentration such as high IL-6 and TNF-α." (PMID 34951691, 2022). "A significant positive correlation was found between the percentage of CD4+IFN-γ+TNF-α− T cell and the tumor size (R = 0.4, P = 0.020), whereas the frequency of CD4+TNF-αhi T cells correlated inversely with the tumor size (R = − 0.3, P = 0.045)." (PMID 36376825, 2022). "Inflammatory cytokines such as IFN-γ and TNF-α induce the production of CSF-1 by tumor cells, which prompts M2 TAM activation or recruitment into the TME." (PMID 35345849, 2022). "We further demonstrate that anti-PD-L1 therapy stimulates TNF-α secretion in vivo as well as in vitro with a prominent role, as source and sentinel, for the tumor-infiltrating monocytes." (PMID 35493461, 2022). "Immune-suppression was also connected to TNFα presence in cancer and studies in animal models have greatly supported its tumor- and metastasis-promoting roles." (PMID 35663982, 2022). "Tumor cells secrete proinflammatory factors, such as TNF-α and IL-12, and these factors recruit neutrophils to flow into the tumor site." (PMID 36111233, 2022). "They reported that benign prostate tissue had higher expression of IL-6 mRNA than matched patient tumor samples while TNFα expression remained unchanged." (PMID 36371231, 2022). "The authors used the model to investigate the tumor response to different regimes with tumor necrosis factor supplies (TNF) and reported complex behaviors in the simulated conditions." (PMID 35463947, 2022). "The ten pathways in which IRF-2 was most affected by GO analysis included the tumor necrosis factor-mediated signaling pathway and the Wnt/β-catenin signaling pathway, both of which were related to tumor development and progression." (PMID 35115027, 2022). "It was reported that proinflammatory cytokines TNF-α, IL-6, and IL-1β are crucial to immune response, inflammatory, and hematopoiesis, as well as development and progression of tumor." (PMID 35210942, 2022).